FHIT (fragile histidine triad diadenosine triphosphatase)
Diseases named in the same sentence as FHIT in open-access papers (continued):
Sharing a sentence is not in itself a finding about the gene and the disease.
adrenocortical carcinoma (1 paper, 2008). "Because FHIT is a tumor suppressor gene, the expression level of FHIT in adrenocortical hyperplasia is high, and in adrenocortical carcinoma is low." (PMID 18366613, 2008). "Or when the expression of FHIT is weakly positive, Ki-67 and PCNA is both strongly positive, adrenocortical carcinoma is suggested, too." (PMID 18366613, 2008). "Found in this study, expression of FHIT in adrenocortical carcinoma is negative or weakly positive, and expression rate is the lowest (P<0.0005)." (PMID 18366613, 2008). "When the expression of FHIT is negative but both of Ki-67 and PCNA are strongly positive, adrenocortical carcinoma is suggested." (PMID 18366613, 2008).
Alzheimer disease (1 paper, 2017). A progressive, neurodegenerative disease characterized by loss of function and death of nerve cells in several areas of the brain leading to loss of cognitive function such as memory and language. "For instance, it was found that LDW could simultaneously disturb the regulations of apoptosis and protein ubiquitination among biological processes, such as RPS6KA1, FHIT and AMFR, which may be the therapeutic targets of Alzheimer Disease." (PMID 29212201, 2017).
brain tumors (1 paper, 2011). "(a) FHIT (the fragile histidine triad gene) is believed to be a tumor suppressor, consistent with its deletion in a number of tumor types, including primary brain tumors." (PMID 21827660, 2011).
carcinosarcoma (1 paper, 2019). A malignant tumor composed of a mixture of carcinomatous and sarcomatous elements. "Because FHIT was normally expressed while miR30c was downregulated, not both downregulated as is the case in several other carcinomas, alterations of the epithelial-mesenchymal transition through an as yet unknown mechanism seems to be a feature of carcinosarcomas." (PMID 31217897, 2019).
cervical tumors (1 paper, 2015). "Several human genes that encode functional inhibitors of the Wnt pathway have been reported to be methylated in cervical tumors including WIF1, CDH1, FHIT, APC, the SLIT2/ROBO family and the SRFP family." (PMID 25826459, 2015).
cleft lip (1 paper, 2021). Congenital defect in the upper lip where the maxillary prominence fails to merge with the merged medial nasal prominences. "Deleting the FHIT gene has never been reported in disturbing the development of cleft lip and palate and the tooth." (PMID 33732167, 2021).
Cushing syndrome (1 paper, 2008). Cushing's syndrome (CS) encompasses a group of hormonal disorders caused by prolonged and high exposure levels to glucocorticoids that can be of either endogenous (adrenal cortex production) or exogenous (iatrogenic) origin. "While the increasing cell proliferating degrees among different diseases of Cushing's syndrome, the expression level of tumor suppressor gene FHIT is reduced, but tumor proliferating antigens Ki-67 and PCN are increased." (PMID 18366613, 2008). "However most of Cushing's syndrome are benign tumors and, as such, it is reasonable that FHIT and PCNA are dominant features to diagnose different types of hypercortisolism in the intelligent machine." (PMID 18366613, 2008). "To conquer such difficulties, we conducted a survey of human genome and tumor genetics and identified several useful (potential) markers such as the expression profiles of cyclin E, P27kip1, FHIT, Bax, Fas, FasL, PCNA, hTERT and Ki-67 for types of Cushing's syndrome." (PMID 18366613, 2008).
ependymoma (1 paper, 2016). A WHO grade II, slow growing tumor of children and young adults, usually located intraventricularly. "Poor prognostic features were found in two other patients: low expression of PAX8, FHIT, CASP10, CHD2, with high expression of CHD11, FUS, and MTA1 in a patient with Ewing sarcoma, and gain of 1q and loss of 6q and overexpression of TNC, CALB1, PLAG1, ALDH1L1, and RELN in a patient with ependymoma." (PMID 28007021, 2016).
esophageal squamous cell carcinoma (1 paper, 2024). Esophageal squamous cell carcinoma (ESCC) is a type of esophageal carcinoma (EC) that can affect any part of the esophagus, but is usually located in the upper or middle third. "The fragile histidine triad diadenosine triphosphatase (FHIT) gene was found to be associated with genomic stability and tumor progression, and methylation of the FHIT gene usually occurs during the initial phase of esophageal squamous-cell carcinoma." (PMID 39766341, 2024).
Fanconi anaemia (1 paper, 2021). "Among these, there were FHIT, WWOX, FANCC (belonging to the Fanconi anaemia pathway), CADM1, and IMMP2L." (PMID 34187875, 2021).
gastric adenoma (1 paper, 2004). A neoplastic polyp that arises from the stomach. "To clarify the role of the FHIT gene in the development of gastric carcinomas, we compared Fhit expression with Mlh1 and phenotypic expression in gastric adenomas and intramucosal carcinomas." (PMID 14760383, 2004).
gastric tumour (1 paper, 2004). "In gastric carcinomas, alterations at the FHIT locus or reduced expressions of Fhit have been associated with gastric tumour progression and poor survival of cancer patients." (PMID 14760383, 2004).
glomerular disease (1 paper, 2014). "Proceeding from our data supporting the link between RANK and glomerular disease, further attempts seem necessary to elucidate the biological background of SNPs near KCNQ5 and FHIT for renal impairment." (PMID 25478860, 2014).
hypercortisolism (1 paper, 2008). "We are the first to systematically measure the expression level of FHIT gene transcript and FHIT protein expression in hypercortisolism of adrenocortical diseases." (PMID 18366613, 2008). "The clinical significance of this medical decision system using expression levels of FHIT, Ki-67 and PCNA and 5 related factors is that this system concurred the difficulties of diagnosing hypercortisolism of various adrenocortical diseases." (PMID 18366613, 2008). "Found in this study, there are some rules in expression levels of FHIT, Ki-67, and PCNA in hypercortisolism of various adrenocortical diseases." (PMID 18366613, 2008). "This study found there are some rules in expression levels of FHIT, Ki-67, and PCNA in hypercortisolism of various adrenocortical diseases." (PMID 18366613, 2008). "Multivariate ordinal logistic regression analysis found that only FHIT and PCNA are strongly related factors of hypercortisolism of various adrenocortical diseases." (PMID 18366613, 2008). "The results suggested that FHIT and PCNA are the more closely related factors for diagnose of hypercortisolism of various adrenocortical diseases." (PMID 18366613, 2008).
Hypodontia (1 paper, 2021). The absence of five or less teeth from the normal series by a failure to develop. "In addition, FHIT loss was reported to be associated with the NSCL/P with hypodontia development." (PMID 33732167, 2021). "A significant decreased of FHIT copy number in NSCL/P with hypodontia (2.10 ± 0.231) compared with normal control (2.01 ± 0.069) was confirmed; p = 0.002." (PMID 33732167, 2021). "A lower 3p14.2 copy number containing a FHIT gene was identified among NSCL/P patients with hypodontia." (PMID 33732167, 2021). "This novel finding would help to shed light on the regulation of SKI and FHIT on the orofacial cleft and hypodontia formation." (PMID 33732167, 2021). "The genes SKI and FHIT were randomly selected from significant CNVs (1p36.33 and 3p14.2) regions to identify their association with NSCL/P and hypodontia." (PMID 33732167, 2021). "Thus, this would be the first finding that revealed FHIT dysregulation in patients affected with NSCL/P with hypodontia." (PMID 33732167, 2021).
intraductal papilloma (1 paper, 2007). An intraluminal papillary epithelial neoplasm arising within the ducts. "In a study of 45 cancers, LOH at the FHIT locus 3p14.2 was found in five out of 45 (11%) of cancer-associated pre-neoplasia (grades not specified but included UDH, apocrine metaplasia, DCIS and intraductal papilloma) and 20 out of 44 (45%) cancers." (PMID 17164758, 2007). "In the breast, loss of heterozygosity (LOH) at the FHIT locus has been observed in 45% of invasive cancers (Ca) and in 11% of unspecified preneoplastic lesions including usual type ductal hyperplasia (UDH), aprocrine metaplasia, DCIS and intraductal papilloma." (PMID 17164758, 2007).
large cell neuroendocrine carcinoma (1 paper, 2012). A usually aggressive carcinoma composed of large malignant cells which display neuroendocrine characteristics. "Large cell neuroendocrine carcinoma—has specific genetic characters similar to SCLC: allelic losses of 3p21, FHIT, 3p22–24, 5q21 (more frequent in SCLC than in LCNEC), 9p21 and the RB gene." (PMID 24213466, 2012).
mesothelioma (1 paper, 2013). A usually malignant and aggressive neoplasm of the mesothelium which is often associated with exposure to asbestos. "Allelic losses at three known tumour suppressor regions (22q which includes Nf2 marker (NF2CA3), 9p for the p16 gene, and 3p for FHIT gene) and at other areas of 14q and 6q, are also frequent in mesothelioma." (PMID 23516439, 2013).
odontogenic cyst (1 paper, 2021). A cyst in the jaw that arises from tissues of tooth development.
ovarian tumors (1 paper, 2017). "FHIT does not seem to enhance miR-30c expression in ovarian tumors, so probably other causes act together with genomic imbalances leading to miR-30c deregulation." (PMID 28423547, 2017). "This does not seem to be the case for ovarian tumors as both FHIT and HMGA2 were found expressed in all tumors analyzed." (PMID 28423547, 2017).
pancreatic ductal adenocarcinoma (1 paper, 2018). An infiltrating adenocarcinoma that arises from the epithelial cells of the pancreas. "The loss of fragile histidine triad protein (FHIT) is strongly related to pancreatic ductal adenocarcinomas." (PMID 29697361, 2018).
parathyroid cancer (1 paper, 2021). "Tumor suppressor fragile histidine triad (FHIT), a target gene for lnc-FEZF2–9:2, was also down-regulated in parathyroid cancer." (PMID 33910638, 2021).
serous adenocarcinoma (1 paper, 2001). An adenocarcinoma that is characterized by the presence of papillary patterns and cellular budding. "Most notably, loss of normal FHIT transcript and impaired expression of Fhit protein occurred only in serous adenocarcinomas of grade 2 and 3 (5/15; 33% and 6/19; 32%, respectively)." (PMID 11461085, 2001).
tuberculosis (1 paper, 2025). A chronic, recurrent infection caused by the bacterium Mycobacterium tuberculosis. "Notably, this research represents the first comprehensive identification of significant differential expression patterns of FHIT, MAN1C1, SLC4A7, NT5E, and other genes in patients with tuberculosis (TB)." (PMID 40524207, 2025). "Transcriptomic profiling identified five metabolically significant differentially expressed genes (FHIT, MAN1C1, SLC4C7, NT5E, AKR1C3; p < 0.05) that effectively distinguish between latent tuberculosis infection (LTBI) and active tuberculosis (TB)." (PMID 40524207, 2025).
urothelial carcinoma (1 paper, 2017). A malignant neoplasm derived from the transitional epithelium of the urinary tract (urinary bladder, ureter, urethra, or renal pelvis).
tumor (185 papers, 1998 to 2026). "The FHIT gene, a canonical tumor suppressor, encodes a critical dinucleotidase that orchestrates purine catabolism, modulates HER2 signaling, and contributes to immune evasion." (PMID 40524207, 2025). "Although some studies have shown that the loss of FHIT function is related to the acceleration of tumor cell proliferation, the role of FHIT in tumor is still controversial." (PMID 40740246, 2025). "Altered expression of FHIT is one of the potential mechanisms that promote tumor progression and its decreased expression is associated with signaling pathways in various cancers." (PMID 38587694, 2024). "The FHIT gene acts as tumor suppressive gene and its tumor suppressive properties have been shown to be restored by transfection of FHIT in FHIT‐deficient human cancer cells that emerge to stimulate apoptosis and hamper cellular growth." (PMID 38587694, 2024). "FHIT gene has been associated with a wide range of tumor-suppressive properties like down-regulation of oncogene activity, apoptosis, invasion, and metastasis." (PMID 38587694, 2024). "Another tumor suppressor, FHIT, which is implicated in tumour growth suppression, as well as in the induction of apoptosis, also has obvious methylation in EBVaGC." (PMID 35763069, 2022). "FHIT inactivation appears to be a later event, possibly associated with progression to more aggressive neoplasms." (PMID 36161592, 2022). "Although the biological function of FHIT has been implicated to be associated with tumor progression, to the best of our knowledge, this was the first report implicating aberrant DNA hypermethylation of FHIT in IBD pathogenesis." (PMID 33946400, 2021). "There are also various reports of genetic variations at the FHIT locus and loss of FHIT protein expression in preneoplasias, proposing a tumor-suppressive role for FHIT in the early stages of cancer progression." (PMID 33732167, 2021). "FHIT belongs to the histidine triad gene family, which encodes a hydrolase of Ap3A, and the FHIT-Ap3A enzyme-substrate complex plays a role as a tumor suppressor." (PMID 32375395, 2020). "FHIT loss on cancer cells favors tumor progression and metastasization and is associated with a poor prognosis." (PMID 32545680, 2020). "Fhit knockout mice show significantly increased susceptibility to cancer development, and FHIT gene therapy prevents or reduces tumor burdens in carcinogen-exposed Fhit-deficient mice." (PMID 30770797, 2019). "FHIT encodes the fragile histidine triad protein and is a tumour suppressor gene that has been linked to cancers of the digestive tract." (PMID 27666579, 2016). "Tumors with FHIT expression level <0.5 (tumor/normal) were considered FHIT-low, as it is known that loss of one FHIT allele causes haploinsufficiency for previously studied Fhit functions." (PMID 25401976, 2015). "For example, there was an increase in formation of spontaneous tumours and susceptibility to carcinogen-induced tumours in FHIT knockout mice compared to mice with functional FHIT." (PMID 26448938, 2015). "The FHIT gene encodes a protein that is both a tumor suppressor and a genome caretaker and has a role in various processes, including production of and response to oxidative damage, that are involved in the generation of precancerous lesions." (PMID 24901304, 2014). "In summary, there is a complex relationship between FHIT expression, ROS, and oxidative stress that plays a role in protection from or susceptibility to mutations and tumor development." (PMID 24901304, 2014). "A main goal of this research will be to define early changes in FHIT-deficient preneoplastic cells that will provide targets to prevent progression to neoplasia." (PMID 24901304, 2014). "The mutations acquired by cells are important for the development of numerous phenotypes necessary for subsequent tumor development; FHIT-deficient cells, being genomically unstable, are more likely to acquire the mutations necessary for cancer development." (PMID 24901304, 2014).
tumor (continued). "Tumor stage, metastasis and presence of lymphatic invasion were significantly linked with the presence of methylated FHIT (p-values 0.001, 0.047 and 0.004, respectively)." (PMID 23573237, 2013). "The role of FHIT in tumor suppression is perhaps best exemplified by studies performed with FHIT-deficient mice." (PMID 23947369, 2013). "Our findings support a model for the initiation of genome instability in early stages of neoplasia through FHIT/FRA3B alterations and subsequent loss of Fhit function." (PMID 23209436, 2012). "In a variable percentage of cases, depending on the tumour type, FHIT loss of function is determined by the hypermethylation status of the associated CpG island with the consequent repression of gene transcription." (PMID 22424615, 2012). "FHIT is the first oncosuppressor gene whose aberrant expression has been associated to equine sarcoids whereas it is frequently altered in human tumours associated to papillomavirus infection." (PMID 23140380, 2012). "FHIT knockout mice developed spontaneous tumours and are more susceptible to cancer than wild-type mice." (PMID 22295218, 2011). "The bioinformatics studies showed that in a great variety of human tumors or tumor cell lines, the FHIT gene presents frequent homozygous deletion, loss of heterozygosity (LOH) and abnormal transcription." (PMID 18366613, 2008). "In ovarian and melanoma cancers, Ap4A functions largely as a suppressor of proliferation and transcriptional activation, whereas in gastrointestinal cancers, dysregulation of its metabolism through loss of FHIT may promote tumor progression." (PMID 40807231, 2025). "FHIT is a member of the histidine triad gene family and encodes a diadenosine P1, P3-bis(5′-adenosyl)-triphosphate adenylohydrolase, which is involved in purine metabolism and works as a tumor suppressor." (PMID 39728796, 2024). "FHIT (fragile histidine triad) belongs to the histidine triad gene family, which encodes Hydrolase of Ap3A, and the FHIT-Ap3A enzyme-substrate complex appears to be the tumor suppressor signal." (PMID 28036263, 2017). "Similarly, the same authors also reported that viral vector-mediated FHIT gene transfer to FHIT-deficient mice not only prevented but also reversed carcinogen-induced tumor development in vivo." (PMID 25875960, 2015). "Thus, FHIT, whose expression is lost or reduced in many human cancers, is a tumor suppressor and genome caretaker whose loss initiates genome instability in preneoplastic lesions." (PMID 24901304, 2014). "Loss of FHIT, a tumor suppressor that functions as a sensor of genotoxic stress, may confer resistance to and permit accumulation of DNA damage." (PMID 24454681, 2014). "FHIT is a proapoptotic tumor suppressor gene that encodes the fragile histidine triad protein (FHIT, also known as bis-(5’-adenosyl) triphosphatase), and FHIT inactivation or loss occurs in many tumor types." (PMID 25024751, 2014). "Furthermore, Fhit knockout (Fhit-/-) mice are highly susceptible to carcinogen-induction of tumors and FHIT replacement in these tumors, by gene therapy, induced apoptosis and significantly reduced tumor burden." (PMID 24244712, 2013). "FHIT is frequently involved in biallelic loss and other chromosome abnormalities in tumours." (PMID 22295218, 2011). "Fragile histidine triad (FHIT) gene encodes a putative tumour suppressor protein." (PMID 22295218, 2011). "Moreover, down-regulation of FHIT protein expression is associated with highly proliferative and large tumours." (PMID 22295218, 2011). "Recently, it has been reported that the FHIT gene may be a target of damage in some of mismatch-deficient tumours." (PMID 14760383, 2004).